GNAS (GNAS complex locus)
Diseases named in the same sentence as GNAS in open-access papers (continued):
Sharing a sentence is not in itself a finding about the gene and the disease.
pseudohypoparathyroidism (continued). "GNAS variants were recently described in 1% of patients not known to have pseudohypoparathyroidism/inactivating PTH/PTHrP signalling disorder 2 in the UK Genetics of Obesity Study." (PMID 39104441, 2024). "Pseudohypoparathyroidism (PHP) and related diseases are associated with a series of pathological changes, neurocognitive, and endocrine abnormalities, mainly due to the GNAS mutation on chromosome 20q13.2, which leads to the weakening of receptor‐mediated hormone signal transduction." (PMID 36669868, 2023). "Pseudohypoparathyroidism is a rare genetic disease characterized by hypocalcaemia and hyperphosphataemia due to the defect to the guanine nucleotide-binding protein alpha subunit (GNAS) gene." (PMID 33422028, 2021). "One FGFR3 mutation (c.1620C>A p.N540K), one likely pathogenic GNAS mutation (c.2288C>T p.A763V), and one TRPS1 mutation (c.2527_c.2528dupTA p.S843fsX72) was identified in three pedigrees with hypochondroplasia, pseudohypoparathyroidism Ia (PHP-Ia), and trichorhinophalangeal syndrome type I (TRPS I)." (PMID 34740356, 2021). "Thus, in pseudohypoparathyroidism, defects in the GNAS gene interfere with PTH signaling in peripheral target tissues, particularly in the kidneys." (PMID 29694629, 2018). "We observed that the PARD6G-AS1 DMR domain is hypomethylated in three imprinted diseases—Beckwith-Wiedemann syndrome, transient neonatal diabetes, and pseudohypoparathyroidism in patients with GNAS cluster imprinting defects —compared with matched control subjects." (PMID 29545821, 2018). "Other molecular defects (for example, modification in GNAS methylation) or defects in other mediators of PTH signaling in target tissues (for example, PRKAR1A) may also cause pseudohypoparathyroidism (A)." (PMID 29694629, 2018). "Pseudohypoparathyroidism (PHP) indicates a group of heterogeneous disorders whose common feature is represented by impaired signaling of hormones that activate Gsalpha, encoded by the imprinted GNAS gene." (PMID 22679513, 2012). "We molecularly diagnosed mutations in CASR, KMT2D, GNAS, PRKAR1A, and CYP27B1, corresponding to cases with clinical diagnoses of isolated hypoparathyroidism/primary hyperparathyroidism, syndromic hypoparathyroidism, pseudohypoparathyroidism, acrodysostosis, and calcipenic rickets." (PMID 41155848, 2025). "Inactivating genetic and epigenetic changes in GNAS, resulting in Gsα deficiency, cause different variants of pseudohypoparathyroidism, which may manifest features of Albright hereditary osteodystrophy (AHO, a syndrome characterized by early-onset obesity and other developmental defects)." (PMID 39684386, 2024). "Pseudohypoparathyroidism 1A (PHP1A) and pseudopseudohypoparathyroidism (PPHP) are caused by loss-of-function variants of GNAS, which encodes Gsα." (PMID 36407415, 2022). "Pseudohypoparathyroidism (PHP) is a rare endocrine disorder derived from the defective activation of the cAMP transduction pathway by the parathyroid hormone (PTH) secondary to molecular defects affecting the alpha subunit of the stimulatory G protein (Gsα), which is encoded by the GNAS gene." (PMID 31555217, 2019). "In contrast, inactivating mutations located on the paternal GNAS allele cause pseudopseudohypoparathyroidism (PPHP) characterized in most patients by several AHO features, but no hormonal resistance, no obesity, and no intellectual challenges." (PMID 32318528, 2020). "When inherited paternally, GNAS mutations cause only AHO but not hormonal resistance, termed pseudopseudohypoparathyroidism (PPHP)." (PMID 21747923, 2011). "In conclusion, somatic GNAS imprinting relaxation and A/B DMR methylation levels have little effect on GNAS expression itself in the context of somatotroph tumors, in contrast to what is observed at the germline level in pseudohypoparathyroidism." (PMID 34299200, 2021).
pseudohypoparathyroidism (continued). "In some cases of pseudohypoparathyroidism (PHP‐1b), the disease is not caused by a mutation in the coding sequence of the maternally inherited GNAS gene but by a deletion within the regulatory regions of the GNAS locus leading to an imprinting defect." (PMID 30349702, 2018). "AHO combined with hormone resistance is called PHP1a, pseudohypoparathyroidism type 1a, whereas AHO that occurs on paternal inheritance of an inactivating GNAS mutation without hormone resistance or severe obesity is called PPHP, pseudopseudohypoparathyroidism." (PMID 23284784, 2012). "In contrast, patients with paternally-inherited GNAS mutations develop pseudopseudohypoparathyroidism (PPHP) and exhibit classic AHO skeletal features but do not exhibit severe obesity or hormonal resistance, [for review]." (PMID 36662765, 2023). "Paternally‐inherited GNAS mutations cause pseudopseudohypoparathyroidism (PPHP), in which patients have AHO skeletal features but do not develop hormonal resistance or marked obesity." (PMID 35079678, 2022). "Methylation defects at GNAS exon A/B alone, or at several GNAS DMRs, are observed in pseudohypoparathyroidism type 1B (PHP1B), characterized by resistance to PTH and frequently TSH, but infrequently by AHO features." (PMID 32318528, 2020). "Pseudopseudohypoparathyroidism (PPHP) patients with an AHO phenotype and no hormone resistance and progressive osseous heteroplasia (POH) cases have inactivating paternally inherited GNAS mutations." (PMID 22679513, 2012). "GNAS imprinting defects have extensively been described in pseudohypoparathyroidism type Ib (PHP-Ib, MIM 623233) patients with hormone resistance to PTH and TSH only and having no AHO." (PMID 22679513, 2012).
fibrous dysplasia (72 papers, 2007 to 2025). A genetic, non-inheritable disorder caused by osteoblastic differentiation defects that result in the replacement of bone marrow and trabecular bone by fibrous stroma and immature bone. "Fibrous dysplasia/McCune Albright syndrome (FD/MAS) is a rare genetic disease caused by postzygotic activating variants in the GNAS gene, encoding the α subunit of stimulatory G protein (Gαs)." (PMID 40781626, 2025). "McCune–Albright syndrome (MAS) is a rare genetic disorder characterized by a triad of café-au-lait spots, fibrous dysplasia, and hyperfunctioning endocrinopathies, resulting from a mosaic mutation in the guanine nucleotide-binding protein (GNAS) gene." (PMID 40917355, 2025). "Fibrous dysplasia/McCune–Albright syndrome (FD/MAS) is a rare condition caused by a mutation in the GNAS locus." (PMID 40297189, 2025). "Fibrous dysplasia (FD) is an uncommon, benign bone disorder caused by a somatic mutation in the GNAS gene on chromosome 20, leading to impaired osteoblastic differentiation and the replacement of normal bone with structurally weak, fibro-osseous tissue." (PMID 40144408, 2025). "Fibrous dysplasia is a benign bone disorder caused by somatic mutations in the GNAS gene and typically presents with symptoms such as conductive hearing loss, facial asymmetry, or vertigo, depending on the involved structures." (PMID 40688862, 2025). "Fibrous dysplasia is associated with mutations in the GNAS gene, which encodes the alpha subunit of the stimulatory G protein." (PMID 40662034, 2025). "Fibrous dysplasia (FD) is a mosaic skeletal disorder caused by somatic activating variants in GNAS, encoding the α subunit of the stimulatory G protein." (PMID 38529507, 2024). "Nevertheless, a search for somatic variants revealed the mosaic pathogenic GNAS variant (p.(Arg201Cys)) which is a well-known cause of fibrous dysplasia." (PMID 38528055, 2024). "The most accepted pathophysiological model proposes that both the fibrous bone dysplasia and intramuscular myxomas develop as a result of a mutation of the GNAS-1 gene, also associated with McCune Albright syndrome and isolated fibrous bone dysplasia." (PMID 39536670, 2024). "Fibrous dysplasia (FD) is a mosaic skeletal disorder caused by somatic activating variants in GNAS, encoding for Gαs, which leads to excessive cAMP signaling in bone marrow stromal cells (BMSCs)." (PMID 38529507, 2024). "Fibrous Dysplasia/McCune–Albright syndrome (FD/MAS) comprises a spectrum of disorders caused by activating somatic mutations in the GNAS gene." (PMID 38255009, 2024). "Fibrous dysplasia (FD) is a mosaic skeletal disorder caused by somatic activating variants of GNAS encoding for Gαs and leading to excessive cyclic adenosine monophosphate signaling in bone-marrow stromal cells (BMSCs)." (PMID 38727310, 2024). "Mazabraud's syndrome is classified within the spectrum of alterations associated with fibrous dysplasia, originated by a mutation in the GNAS-1 gene." (PMID 39536670, 2024). "In this, GNAS gene mutation is present in a very high proportion of the body's cells leading to a more severe and widespread form of fibrous dysplasia." (PMID 39347278, 2024). "Fibrous dysplasia is etiologically associated with mutation in GNAS, whereas the dysregulation of the Wnt and NOTCH pathways has been implicated in the etiopathogenesis of ossifying fibroma." (PMID 37232789, 2023). "Human diseases associated with the GNAS gene encompass fibrous dysplasia (FD), Albright’s Hereditary Osteodystrophy (AHO), parathyroid hormone(PTH) resistance, and Progressive Osseous Heteroplasia (POH), among others." (PMID 37920253, 2023). "Activating mutations in GNAS have been reported to be causative of fibrous dysplasia of bone, a condition characterized by an abnormal differentiation of skeletal progenitor cells with increased osteoclastogenesis, leading to focal osteolytic lesions." (PMID 35769265, 2022).
fibrous dysplasia (continued). "The pathogenesis of fibrous dysplasia is associated with GNAS gene mutations, resulting in dysregulation and overproduction of cAMP, which alters the cellular properties of bone osteoprogenitor cells and leads to abnormal bone development." (PMID 35204329, 2022). "Activating mutations of the GNAS locus are associated with fibrous dysplasia, a disorder of weakened skeletal structure, further highlighting the critical role of the GNAS locus in the formation and maintenance of bone tissues." (PMID 33574833, 2021). "McCune - Albright syndrome is a genetic disease with cutaneous mosaicism caused by post-zygotic activating mutations in GNAS locus, it has a triad of fibrous bone dysplasia, café-au-lait macules and precocious puberty." (PMID 34839987, 2021). "Accordingly, a gain-of-function GNAS mutation results in the aberrant differentiation of BMSCs into osteoblasts, the primary cellular mechanism underlying fibrous dysplasia of bone." (PMID 34220953, 2021). "Additional molecular testing is helpful in differentiating desmoplastic fibroma from low-grade osteosarcoma (MDM2 amplification) and fibrous dysplasia (GNAS mutation)." (PMID 31838586, 2020). "GNAS mutation in fibrous dysplasia leads to increased levels of CAMP, thereby activation of CREB causing increased expression FGF23, resulting in mineralisation defect." (PMID 31838586, 2020). "Fibrous dysplasia (FD) of bone is a complex disease of the skeleton caused by dominant activating mutations of the GNAS locus encoding for the α subunit of the G protein-coupled receptor complex (Gsα)." (PMID 31999703, 2020). "Evidently, IDH1/2 and GNAS mutations are examples of useful molecular markers pathognomonic for chondrosarcoma and fibrous dysplasia, respectively." (PMID 31838586, 2020). "Markers in the GNAS locus are also associated with endocrine tumors, fibrous dysplasia of bone and hereditary osteodystrophy." (PMID 33175867, 2020). "Fibrous Dysplasia / McCune Albright syndrome (FD/MAS) represents a wide spectrum of diseases due to somatic gain-of-function mutations of the GNAS gene." (PMID 31196103, 2019). "Mazabraud’s syndrome and the closely related McCune-Albright syndrome, which is associated with fibrous dysplasia, café au lait macules and endocrine disorders, are caused by activating missense mutations in codon 201 of the GNAS gene." (PMID 30736805, 2019). "GNAS activation or loss-of-function mutations in humans cause fibrous dysplasia (FD) or progressive osseous heteroplasia (POH) that shows craniofacial hyperostosis or craniosynostosis, respectively." (PMID 30479847, 2018). "Fibrous dysplasia (FD) presents as skeletal lesions in which normal bone is replaced by abnormal fibrous tissue due to mosaic GNAS mutation." (PMID 29599748, 2018). "Guanine nucleotide-binding protein/α-subunit (GNAS) mutations are involved in fibrous dysplasia (FD) pathogenesis." (PMID 28588314, 2017). "Fibrous dysplasia (fibrous dysplasia) is a rare benign bone disease caused by a postzygotic, activating mutation of the GNAS gene, which alters the signaling of G-protein at the cellular level." (PMID 27020436, 2017). "Several diseases result from GNAS mutations, including those that activate Gsα (McCune-Albright Syndrome and fibrous dysplasia of the bone) and those that inhibit Gsα, such as AHO and pseudohypoparathyroidism." (PMID 27579188, 2016). "GNAS (guanine nucleotide-binding protein/α-subunit) mutations that induce the activation of G-protein α-subunit participate in the pathogenesis of fibrous dysplasia." (PMID 24678936, 2014). "There is a well-established association between fibrous dysplasia and post-zygotic activating mutations of the GNAS gene." (PMID 24678936, 2014). "Fibrous dysplasia is a genetic disease caused by postzygotic, activating mutations of the GNAS gene, which impair the GTPase activity of Gs-alpha thus resulting in excess intracellular cAMP." (PMID 19025620, 2008).
fibrous dysplasia (continued). "Fibrous dysplasia has been shown to harbor a missense mutation at codon 201 in exon 8 of GNAS." (PMID 40075784, 2025). "Intramuscular myxoma, Mazabraud’s syndrome and the closely related McCune-Albright syndrome (also associated with fibrous dysplasia, café au lait macules and endocrine disorders) are mostly caused by the activating missense mutations in codon 201 or codon 227 of the GNAS complex locus gene (GNAS)." (PMID 38317844, 2024). "The currently available evidence suggests that the association with intramuscular myxomas is more frequent in cases of polyostotic fibrous dysplasia, possibly due to a more generalized tissue distribution of the mutation in the GNAS-1 gene, extending to soft tissues." (PMID 39536670, 2024). "GNAS-activating somatic mutations give rise to Fibrous Dysplasia/McCune–Albright syndrome (FD/MAS)." (PMID 38255009, 2024). "Considering the combination of GNAS mutation with one of the typical clinical triad characteristics, fibrous dysplasia of bone, we diagnosed this patient with McCune-Albright syndrome accompanied by ACTH-independent Cushing's syndrome caused by an ectopic residual adrenal tumor due to GNAS mutation." (PMID 35966069, 2022). "Histopathologically, the differential diagnosis still presents difficulties due to morphological overlaps, unless characteristic mutational analysis of the alpha subunit of the G protein gene (GNAS) reveals mutation and therefore leads to the diagnosis of fibrous dysplasia." (PMID 35204329, 2022). "The remaining three patients harboured the R201 GNAS mutation characteristic of fibrous dysplasia." (PMID 34528398, 2021). "Germline GNAS mutations are associated with McCune-Albright syndrome and fibrous dysplasia." (PMID 32127014, 2020). "McCune-Albright syndrome (MAS) is characterized by the triad of precocious puberty, café au lait pigmentation, and polyostotic fibrous dysplasia (FD) of bone, and is caused by post-zygotic somatic mutations—R201H or R201C—in the guanine nucleotide binding protein, alpha stimulating (GNAS) gene." (PMID 29104223, 2017). "GNAS mutation has been found in various tumours, fibrous dysplasia, and McCune-Albright syndrome." (PMID 27512631, 2016). "GNAS mutation detection may be helpful in differentiating fibrous dysplasia from other fibro-osseous lesions." (PMID 24678936, 2014). "The complexity of the GNAS locus and embryonic lethality of constitutively-active Gsα signaling preclude direct genetic modifications to introduce the classical GNAS mutations that cause fibrous dysplasia." (PMID 24788917, 2014). "Now it is known that fibrous dysplasia, monostotic, polyostotic, or as part of the McCune-Albright syndrome is caused by postzygotic (somatic) mutations in the gene encoding the alpha subunit of the stimulatory G protein within the GNAS complex locus." (PMID 23230423, 2012). "As in patients with MAS, nearly all isolated cases of fibrous dysplasia are associated with GNAS mutations at Arg201; however, a study using a mutation-specific restriction enzyme digest assay has recently identified three Gln227 (to Leu) mutations among a total of 56 samples." (PMID 19412439, 2007). "GNAS-activating mutations have been identified across many cancer types, such as pancreatic adenocarcinoma, squamous cell carcinoma of the head and neck, breast neoplasm, gastric adenocarcinoma, adrenal cortex carcinoma, and sex cord-stromal tumor, as well as in fibrous dysplasia and LSMFT." (PMID 40075784, 2025). "Alternatively, a mechanism of “selective apoptosis” of β-catenin mutated cells, similar to the supposed mechanism of “vanishing” GNAS mutations in long-standing fibrous dysplasia might be postulated to explain the CTNNB1 wild type status of a subset of osteomas." (PMID 34725446, 2022).